MPO (myeloperoxidase)
Diseases named in the same sentence as MPO in open-access papers (continued):
Sharing a sentence is not in itself a finding about the gene and the disease.
atherosclerosis (continued). "Interestingly, many inflammatory disorders such as ovarian cancer and atherosclerosis, in which MPO/HOCl have been known to be elevated, are also associated with significant free iron accumulation." (PMID 25835505, 2015). "A1M can also protect LDL against oxidative damage caused by MPO and may thus have an important role in preventing the formation of atherosclerosis." (PMID 25698971, 2015). "We show that elevated intraplaque MPO activity detected by molecular MRI employing MPO-Gd predicts future atherothrombosis in a rabbit model and detects ruptured human atheroma, strengthening the translational potential of this approach to prospectively detect high-risk atherosclerosis." (PMID 38370393, 2024). "However, it is also possible the reduction of MPO in other cell types such as neutrophils and monocytes could also have contributed to the decrease in atherosclerosis observed in the MPO-deficient state." (PMID 33234591, 2021). "However, the causal relationship between MPO and the development and progression of atherosclerosis in patients with CKD is unknown." (PMID 33234591, 2021). "However, MPO has been linked to atherosclerosis and recurrent coronary events." (PMID 31341419, 2019). "The method allows the anti-MPO antibodies detection, which according to the specialised literature data are implicated particularly in the vascular inflammatory pathogenesis, because of their role as co-participants responsible for the set of vascular dysfunction by atherosclerosis." (PMID 30165747, 2018). "HOCl is generated by myeloperoxidase (MPO) and augmented serum levels of MPO have been described in acute and chronic inflammatory conditions in cardiovascular patients and has been implicated in many inflammatory diseases such as atherosclerosis, neurodegenerative conditions, and some cancers." (PMID 29163665, 2017). "MPO-catalyzed species are involved further in oxidative damage of various biological molecules (e.g., lipids, lipoproteins, and proteins low) and tissue degradation and are implicated in atherosclerosis, cancer, diabetic vascular complications, kidney diseases, and other disorders." (PMID 25821554, 2015). "In light of the increasing body of evidence supporting the role of myeloperoxidase (MPO) in inflammation, atherosclerosis, and acute coronary syndrome, its interaction with captopril has been investigated." (PMID 40806350, 2025). "Upon activation, neutrophils upregulate various integrins and release reactive oxygen species, myeloperoxidase, neutrophil elastase, and matrix metalloproteinases, all of which expedite atherosclerosis progression." (PMID 40270516, 2025). "Overall, the presence and activity of MPO in human atherosclerosis are well established, and MPO colocalizes with macrophages in human atherosclerotic lesions." (PMID 40002748, 2025). "In conditions such as atherosclerosis and aneurysm, oxidative stress, especially from MPO-derived HOCl, can contribute to ECM remodeling." (PMID 41312739, 2025). "In atherosclerosis, increased serum MPO activity leads to oxidative modification of HDL-C, potentially reducing its renoprotective function." (PMID 40909227, 2025). "For example, in atherosclerosis—a persistent immunoinflammatory condition—MPO-derived oxidants contribute to tissue damage, oxidized LDL accumulation, and lesion progression." (PMID 40895555, 2025). "In the context of atherosclerosis, an increase in macrophages with high levels of MPO was observed in eroded or ruptured plaques." (PMID 38367056, 2024). "Plaque MPO activity was assessed in vivo in rabbits (n = 12) using the MPO-gadolinium (Gd) probe at 8 and 12 weeks after induction of atherosclerosis and before pharmacological triggering of atherothrombosis." (PMID 38370393, 2024). "Researchers observed that the inhibition of MPO in a mice model of atherosclerosis reduced both the inflammatory response and endothelial dysfunction." (PMID 38275657, 2024).
atherosclerosis (continued). "In the context of atherosclerosis, MPO is thought to contribute to the oxidative modification of low-density lipoprotein (LDL) cholesterol, a key step in the development of atherosclerotic plaques." (PMID 38396639, 2024). "Whilst MPO has been implicated in exacerbating CAD and atherosclerosis more broadly, its expression and function in endothelial cells has been debated." (PMID 39456241, 2024). "For example, while two studies found that pharmacological inhibition and MPO deletion improved atherosclerosis in mice models, another found that MPO depletion worsened the atherosclerotic condition." (PMID 38673843, 2024). "Elevated plasma MPO levels are frequently detected in patients with atherosclerosis, cardiovascular, respiratory, autoimmune and neurogenerative diseases and cancer, and correlate with disease severity." (PMID 39766232, 2024). "Neutrophils have been associated with the development of CVD, possibly due to occasional overexpression of myeloperoxidase and reactive oxygen species, thereby worsening tissue injury and advancing atherosclerosis." (PMID 39498213, 2024). "This increased detectable MPO in murine lesions and augmented atherosclerosis development by two-fold." (PMID 39061857, 2024). "As such, MPO is a significant therapeutic candidate to alleviate oxidative stress, offering a promising solution to endothelial and mitochondrial dysfunction and atherosclerosis." (PMID 37507899, 2023). "One of the proinflammatory enzymes involved in the process of atherosclerosis is myeloperoxidase (MPO)." (PMID 36902521, 2023). "Certainly, MPO is the most abundant protein in human neutrophils, playing a major role in inflammation, oxidative stress, lipoprotein oxidation, and atherosclerosis." (PMID 36595188, 2023). "Elevated MPO activity is responsible for endothelial dysfunction and atherosclerosis, leading to T2DM vascular complications." (PMID 37569455, 2023). "The CpG site in the third pathway, which is assessed by the cg04988978 MSdPCR assay, maps to the upstream promoter area of myeloperoxidase (MPO), which has been shown to contribute to atherosclerosis by the oxidation of LDL." (PMID 37372412, 2023). "The critical role of MPO in several cardiovascular diseases, such as atherosclerosis, myocardial infarction, arrhythmia, and pulmonary hypertension led to clinical development of oral MPO inhibitors." (PMID 37656254, 2023). "MPO and MPO-derived oxidants can contribute to atherosclerosis by foam cell formation and endothelial dysfunction demonstrated by increased endothelial cell permeability and apoptosis." (PMID 37569455, 2023). "Inhibition of MPO has been demonstrated to reduce endothelial dysfunction in mouse models of vascular inflammation and atherosclerosis." (PMID 37507899, 2023). "The cholesterol efflux process, which plays a protective role in atherosclerosis, is impaired when HDLs are oxidized by MPO." (PMID 35624738, 2022). "The identification of vulnerable and stable plaque is a critical part of atherosclerosis treatment, with myeloperoxidase (MPO) being a potential inflammatory marker of vulnerable atherosclerotic plaque." (PMID 35846005, 2022). "MPO oxidized-LDLs (Mox-LDLs) have multiple effects on cells involved in the development of atherosclerosis." (PMID 35624738, 2022). "HFD-fed ApoE−/− mice irradiated and reconstituted with MPO−/− bone marrow show reduced atherosclerosis; MPO−/− mice and wild-type WT mice treated with an MPO inhibitor show reduced neointima formation following ischemia reperfusion (I/R) injury." (PMID 35883899, 2022). "One of the most studied roles of MPO in atherosclerosis is its involvement in the modification of lipoproteins." (PMID 35624738, 2022). "In atherosclerosis, ROS production is associated with NADPH oxidase (NOX), myeloperoxidase (MPO), eNOS, and lipoxygenase." (PMID 35399657, 2022).
atherosclerosis (continued). "Atherosclerosis is known to be a chronic inflammatory process in which interleukin 6 (IL-6), myeloperoxidase (MPO), matrix metalloproteinase 9 (MMP-9), and intercellular and vascular cell adhesion molecules are used as biomarkers." (PMID 35563387, 2022). "In this review, we discuss the interrelationship between MPO, Mox-LDLs, and resolvins, highlighting a new perception of the role of Mox-LDLs in atherosclerosis." (PMID 35624738, 2022). "On the other hand, there have been experimental data showing an unexpected protective role of MPO in atherosclerosis." (PMID 35205069, 2022). "In this review, we discuss the involvement of MPO and Mox-LDLs in atherosclerosis, and, more specifically, their role in modulating inflammation and its resolution, with a special focus on the resolution of endothelial inflammation." (PMID 35624738, 2022). "Myeloperoxidase (MPO) has been related to oxidative stress and atherosclerosis, and MPO-oxidized low-density lipoproteins (Mox-LDLs) have specific characteristics and effects." (PMID 35624738, 2022). "MPO inhibition improves plaque stability in models of atherosclerosis and has been suggested as a target to prevent plaque rupture." (PMID 36293108, 2022). "Evidence supports the fact that MPO plays a very important role in the pathogenesis of atherosclerosis because it contributes to vascular dysfunction during acute inflammation by modulating the endothelial NO bioavailability." (PMID 36142645, 2022). "Perplexingly, elevated MPO levels are observed in cardiovascular diseases in humans, yet MPO KO animals are more prone to developing atherosclerosis." (PMID 36293108, 2022). "Despite the increased SAA levels, the mice had decreased atherosclerosis highlighting the critical role of MPO in CKD atherosclerosis." (PMID 33234591, 2021). "Oxidative modifications of HDLs and LDLs by myeloperoxidase (MPO) are regularly mentioned in the context of atherosclerosis." (PMID 34500696, 2021). "This difference was explained partly by pointing out differences of both MPO and pathogenesis of atherosclerosis between humans and mice." (PMID 33916434, 2021). "The current study is the first to demonstrate a causal relationship between bone-marrow-derived MPO and CKD-accelerated atherosclerosis." (PMID 33234591, 2021). "In conclusion, we successfully developed a specific nanoprobe (5HFeC NPs) that can be applied in FLI/MPI/CTA multimodality imaging of active MPO in atherosclerosis with high sensitivity." (PMID 33391489, 2021). "The darkseagreen module had 25 genes significantly and jointly associated with early traits of both osteoporosis (RSCoBMC) and atherosclerosis (CIMTavg) in model 1, the most significant (p.adj = 6.8 × 10−24) being Myeloperoxidase (MPO)." (PMID 33782480, 2021). "Enzymatically active MPO has been shown in human vascular atherosclerotic lesions, indicating the involvement of MPO in atherosclerosis." (PMID 34440189, 2021). "Myeloperoxidase (MPO), an enzyme primarily secreted by neutrophils, plays a vital role in the pathogenesis of atherosclerosis, congestive HF, hypertension and other cardiovascular diseases." (PMID 34859069, 2021). "For instance, activated macrophages and foam cells residing in inflammatory atherosclerosis plaques overexpress myeloperoxidase (MPO)." (PMID 34867370, 2021). "The modifications of the protein moiety via the MPO/H2O2/Cl− system have deleterious effects in the context of atherosclerosis." (PMID 34500696, 2021). "In our study, both FLI and MPI/CTA imaging demonstrated that 5HFeC NPs can target active MPO in atherosclerosis." (PMID 33391489, 2021). "In contrast to our work on CKD atherosclerosis, the role of MPO in mouse models of atherosclerosis with preserved renal function has been controversial." (PMID 33234591, 2021). "Some evidence exists that MPO levels are associated with the development of T2DM and its complications, including atherosclerosis and DN." (PMID 34063078, 2021).
atherosclerosis (continued). "Myeloperoxidase is another heme protein believed to participate in the development of atherosclerosis, suggesting a general antioxidation role of A1M in the control of atherosclerosis." (PMID 34206377, 2021). "Multiple epidemiological studies found MPO deficient individuals to be protected from CHD and other clinical manifestations of atherosclerosis." (PMID 33916434, 2021). "This study demonstrates the reduction of atherosclerosis in CKD mice with the deletion of MPO in bone marrow cells, strongly implicating bone-marrow-derived MPO in the pathogenesis of CKD atherosclerosis." (PMID 33234591, 2021). "Nearly 20 years later, another study partially resolved the conundrum of MPO in murine atherosclerosis." (PMID 33916434, 2021). "MPO inhibitors preserve endothelial function in mouse models of atherosclerosis with intact renal function by oxidizing soluble guanylyl cyclase resulting in improvement in plaque area, cytokine levels, and oxidative stress." (PMID 33234591, 2021). "Overall, our study provides evidence of a causal role of bone-marrow-derived MPO in the pathogenesis of atherosclerosis in CKD mice and identifies MPO as a potential therapeutic target in CKD-accelerated atherosclerosis." (PMID 33234591, 2021). "Surprisingly, the SAA levels were elevated in the CKD-bMPOKO mice despite decreased atherosclerosis, suggesting that MPO expression was the primary driver of this phenotype (p < 0.05." (PMID 33234591, 2021). "This integral step in the pathogenesis of atherosclerosis is promoted by the oxidative capabilities of MPO." (PMID 33916434, 2021). "Association of MPO with HDL has previously been shown to reduce the PON1 activity of HDL and to correlate with increased atherosclerosis." (PMID 34331945, 2021). "Atherosclerosis is a complex process in which the leukocyte-derived enzyme myeloperoxidase (MPO) plays an important role." (PMID 34640592, 2021). "These are found in a variety of conditions including infection, malignancy, atherosclerosis, and autoimmune diseases, and they contain cell free DNA (cf-DNA), myeloperoxidase (MPO), histone, neutrophil elastase (NE), and several other antibacterial proteins." (PMID 34539623, 2021). "Increased myeloperoxidase activity correlates with the severity of atherosclerosis and the level of calcium in the walls of the coronary arteries." (PMID 32570831, 2020). "MPO plays important roles in the inflammatory response and perpetuation of chronic inflammation in atherosclerosis." (PMID 31979310, 2020). "ROS/RNS generated during inflammation is associated with the progress of a variety of diseases such as Alzheimer, atherosclerosis, cancer, etc., and MPO has been shown to be a biomarker of myocardial infarction and coronary artery disease." (PMID 33344116, 2020). "Our results suggest that the MPO c.−463AA and PON1 c.575GG genotypes increase the risk of more severe atherosclerosis." (PMID 32961879, 2020). "MPO also initiates/promotes acute and chronic inflammation, as well as atherosclerosis by the production of pro-oxidants such as HOCl and tyrosyl radicals." (PMID 33158288, 2020). "Inactivation of MPO reduced reactive oxygen species (ROS)-mediated vascular inflammation and atherosclerosis." (PMID 31979310, 2020). "Studies have also shown that decreased HDL apoAI exchangeability is associated with the presence of atherosclerosis in humans, raising the possibility that MPO-mediated MDA modification of HDL impacts atherosclerosis development." (PMID 32629758, 2020). "We analyzed mean HbA1c value from all years of disease, BMI, blood pressure, lipids, new biomarkers of atherosclerosis (hsCRP, adiponectin, myeloperoxidase, NT-proBNP peptide, vitamin D), and cIMT of common carotid arteries." (PMID 32793113, 2020). "It was previously reported that pharmacological inhibition of MPO by 4-aminobenzoic acid hydrazide reduces plaque formation in the mouse apolipoprotein E knockout (ApoE−/−) model of atherosclerosis." (PMID 32899436, 2020).
atherosclerosis (continued). "Previous studies with other MPO inhibitors have also demonstrated reductions in necrotic core area along with increased collagen content in mouse models of atherosclerosis and plaque vulnerability." (PMID 30889221, 2019). "In previous studies, a direct inhibition of MPO via 4-aminobenzoic acid hydrazide (4-ABAH) or other small molecules has been found to decrease the development of atherosclerosis." (PMID 30939159, 2019). "Although UCP had relatively lowest activity in scavenging HOCl, its possible role in modulation of myeloperoxidase-induced cell damage in inflammatory diseases, such as neurodegenerative disease and atherosclerosis, requires further investigations." (PMID 31320913, 2019). "Even though a strong correlation has been found between atherosclerosis, inflammatory diseases, and MPO release, little work has been done to inhibit MPO to suppress these diseases." (PMID 29669993, 2018). "Myeloperoxidase (MPO) is a leukocyte-derived heme protein bound to HDL and is linked to enhanced oxidative stress and atherosclerosis." (PMID 30002679, 2018). "Another major player in the acceleration of vascular injury and atherosclerosis is the elevated level of myeloperoxidase (MPO) which is present in leukocytes, monocytes and tissue macrophages, and promotes the peroxidation of LDL cholesterol." (PMID 30534079, 2018). "Plasma LDL interacts with circulating MPO, which has been reported to be higher in patients suffering from atherosclerosis." (PMID 29669993, 2018). "For example, in atherosclerosis the release of matrix modifying mediators such as neutrophil elastase (NE), myeloperoxidase (MPO), and defensins by activated neutrophils leads to the formation and development of atherosclerotic plaques." (PMID 30356867, 2018). "MPO is a potential participant in promotion and propagation of atherosclerosis and impairing endothelial function, it can participate in destabilization of atherosclerotic plaques." (PMID 29618370, 2018). "MPO could be secreted in the extracellular space; augmented serum levels of MPO have been described in acute and chronic inflammatory conditions in cardiovascular patients and have been implicated in many inflammatory diseases such as atherosclerosis, neurodegenerative conditions, and some cancers." (PMID 29163665, 2017). "MPO-transgenic mice, whose macrophages expressed human MPO, revealed more severe lesion of atherosclerosis." (PMID 27167346, 2016). "MPO oxidizes both protein and lipid components, increasing their atherogenicity and promotes pathogenesis of atherosclerosis." (PMID 27167346, 2016). "The serum levels of atherosclerosis-related biomarkers, such as asymmetric dimethylarginine (ADMA), myeloperoxidase (MPO) and adiponectin, were measured by enzyme-linked immunosorbent assay." (PMID 26179062, 2015). "Further studies are needed to elucidate the actual mechanism behind the contribution of MPO to the development of atherosclerosis and to assess the potential of apoA-I/apoA-II heterodimers as a biomarker for estimating the anti-inflammatory ability of HDL." (PMID 26257958, 2015). "The exact roles of high FPG, MPO and their relation in the atherosclerosis have been completely clarified, it needs further investigation." (PMID 26307104, 2015). "The key role of MPO in atherosclerosis has been demonstrated as MPO can oxidize both low-density lipoprotein (LDL) and high-density lipoprotein (HDL), triggering endothelium inflammation and inhibiting the cholesterol efflux, respectively." (PMID 24514562, 2014). "MPO activity has been suggested to contribute to the pathogenesis of degenerative diseases, including atherosclerosis, multiple sclerosis and Alzheimer disease." (PMID 23734221, 2013).